ERBB3 (erb-b2 receptor tyrosine kinase 3)
Diseases named in the same sentence as ERBB3 in open-access papers (continued):
Sharing a sentence is not in itself a finding about the gene and the disease.
invasive breast carcinoma (10 papers, 2008 to 2025). A carcinoma that infiltrates the breast parenchyma. "Up-regulation of ERBB3 (HER3) has been connected with invasive breast carcinomas and also drug resistance in some HER2-overexpressing cancers." (PMID 22709873, 2012). "HRGβ overexpression in a large percentage of invasive breast cancers, and its ability to reduce the in vitro efficacy of trastuzumab against BT-474 cells, emphasizes the need to effectively compete for ligand-dependent activation of ERBB3." (PMID 25386657, 2014). "ERBB2 and ERBB3 somatic gain-of-function mutations, which may be targeted by anti-ERBB2 therapies, were reported by high-throughput sequencing studies in 1% and 2% of invasive breast cancers respectively." (PMID 27602491, 2016). "Immunohistochemical studies have shown that ErbB3 is expressed or overexpressed in greater than 50% of DCIS and invasive breast cancers and correlates with poor prognosis." (PMID 18841159, 2008).
pancreatic ductal adenocarcinoma (10 papers, 2011 to 2026). An infiltrating adenocarcinoma that arises from the epithelial cells of the pancreas. "A few of these recurrent neoantigens are from known oncogenic drivers, for example, PIK3CA, MAPK1, ERBB2, ERBB3, and also from the KRAS G12D mutation, which we recently identified as a promising recurrent neoantigen-based immunotherapy target in pancreatic ductal adenocarcinoma." (PMID 28670312, 2017).
type 1 diabetes (10 papers, 2010 to 2024). "Genetic variation in the ERBB3/IKZF4 region was repeatedly associated with type 1 diabetes and used to improve prediction of islet autoimmunity and disease progression." (PMID 34448034, 2021). "A protein–protein interaction network was linked to type 1 diabetes-associated genes with differentially expressed seroconversion genes, revealing direct interactions with ERBB3 and GLIS3, two type 1 diabetes susceptibility genes." (PMID 32797243, 2020). "PrediXcan confirmed the association between ERBB3 and type 1 diabetes and found that low ERBB3 expression increased disease risk." (PMID 32477401, 2020). "In siblings and offspring of type 1 diabetes patients, polymorphism in region ERBB3/IKZF4 may affect disease progression at the level of epitope spreading in female individuals." (PMID 34448034, 2021). "As an illustration, a SNP nearby ERBB3 had been previously associated with type 1 diabetes." (PMID 32477401, 2020). "The purpose of this study was to explore the association between rs2292239 polymorphism in ERBB3 gene and type 1 diabetes (T1D)." (PMID 31467911, 2019). "Our findings suggest that interaction between sex and ERBB3/IKZF4 may contribute to the post-pubertal male excess in type 1 diabetes." (PMID 34448034, 2021). "We examined whether the non-HLA susceptibility locus ERBB3/IKZF4 influences progression of type 1 diabetes stage specifically according to sex." (PMID 34448034, 2021). "SNPs of ERBB3 (rs2292239 T/G) and IKZF4 (rs1701704 G/T) were screened by allelic discrimination quantitative PCR assay in first-degree relatives of type 1 diabetes patients who had developed at least one circulating autoantibody." (PMID 34448034, 2021). "The progression from multiple autoantibody positivity to type 1 diabetes appeared not to be influenced by ERBB3/IKZF4." (PMID 34448034, 2021).
cutaneous melanoma (9 papers, 2010 to 2025). A primary melanoma arising from atypical melanocytes in the skin. "In the immunohistochemistry supplied by the HPA data set, we discovered that ERBB1 was moderately expressed, ERBB2 was lowly expressed, and the ERBB3/4 proteins were highly expressed in cutaneous melanoma." (PMID 33732282, 2021). "By contrast, the ERBB3 expression level was higher in cutaneous melanoma than in normal skin tissue." (PMID 33732282, 2021). "In Riker’s and Talantov’s datasets, ERBB3 is overexpressed compared with the normal samples: cutaneous melanoma with a fold change of 4.667 and 2.264, respectively." (PMID 33732282, 2021). "Overexpression (such as for ERBB3) is a clinicopathological characteristic in cutaneous melanoma." (PMID 38732371, 2024). "In cutaneous melanoma, ERBB3 high expression and ERBB1/2 low expression were strongly associated with 5 years survival rates of cutaneous melanoma patients but may not affect tumor stage or disease-free survival." (PMID 33732282, 2021). "ERBB3 was upregulated in cutaneous melanoma in two datasets." (PMID 33732282, 2021). "The four ERBB tyrosine kinase family members [ERBB1 (epidermal growth factor receptor, EGFR), ERBB2 (HER2), ERBB3 (HER3), and ERBB4 (HER4)] (ERBB receptor family) have been shown, according to previous studies, to be related to the cutaneous melanoma." (PMID 33732282, 2021). "The results showed that, compared with normal skin tissue, cutaneous melanoma tissue had lower expression levels of ERBB1/2 and a higher expression level of ERBB3." (PMID 33732282, 2021). "Low expression of ERBB1/2 and high expression of ERBB3 were detrimental to the 5 years survival of cutaneous melanoma patients (ERBB1: log-rank P: 0.03; ERBB2: log-rank P: 0.008; ERBB3: log-rank P: 0.039)." (PMID 33732282, 2021). "In our report, we confirmed that ERBB3 exhibits high expression and influences the 5 years survival rates of cutaneous melanoma patients but may not play role in the tumor stage and disease-free survival." (PMID 33732282, 2021).
metastatic colorectal cancer (9 papers, 2017 to 2025). "Moreover, a significant number of HER2-mutated and ERBB3-mutated samples associated with MSI have been found in metastatic colorectal cancer, theorizing the possibility of combining immunotherapy with anti-HER2 agents for these patients." (PMID 34070574, 2021).
pancreatic adenocarcinoma (9 papers, 2007 to 2025). "Two patients received therapies following the recommendations of the local molecular tumor board, as mutations with only low or no levels of evidence for actionability were detected (BRCA2 S497L in pancreatic adenocarcinoma; ERBB3 G284R in CCC)." (PMID 38664720, 2024). "In vivo and in vitro experiments from another study conducted by Liles JS confirmed that high expression of ERBB3 promotes tumorigenesis of pancreatic adenocarcinoma." (PMID 34321959, 2021).
brain tumors (7 papers, 2019 to 2025). "We observed lower incidences of KDD in ERBB2, ERBB3 and ERBB4 than EGFR, with distributions mirroring those of other observed oncogenic mutations in brain tumors and NSCLC13–17." (PMID 33654076, 2021).
colorectal tumors (7 papers, 2006 to 2019). "Expression of ERBB3 and intestinal stem cell markers were significantly elevated in adenomas and colorectal tumours compared to normal tissue." (PMID 26367378, 2015). "In various types of cancer, including tumors of the head, neck, lung, and breast and colorectal tumors, the ErbB family of receptors (EGFR/HER1/ERBB1, HER2/neu/ERBB2, HER3/ERBB3, and HER4/ERBB4) is unregulated, producing an inappropriate cell stimulation." (PMID 30670929, 2018). "Expression of ERBB3 and intestinal stem cell markers (LGR5, EPHB2, CD44s and CD44v6) was assessed by qRT-PCR in primary colorectal tumours (stages 0 to IV) and matched normal tissues from 53 patients." (PMID 26367378, 2015). "In addition, in the cell lines that contained a detectable and robust ERBB3 cell population (LIM1215 and LIM1899), EPHB2 and ERBB3 marked distinct cell populations, as observed in our study in human colorectal tumours." (PMID 26367378, 2015). "In addition, colorectal tumours that did not contain any MUC2+ cells still had an EPHB2-/ERBB3+ cell population (data not shown)." (PMID 26367378, 2015).
metastatic melanoma (7 papers, 2015 to 2025). A melanoma that has spread from its primary site to another anatomic site. "Taken together, our findings support the concept that triple therapy directed against BRAF/MEK/ErbB3 may be able to provide durable control of BRAF mutated metastatic melanoma." (PMID 26208478, 2015).
bladder tumors (6 papers, 2006 to 2022). "In all, this evidence suggests a “class-switch” from ErbB3 to EGFR/ErbB2 mediated ErbB signaling, mediated in part by collagen and fibronectin-stimulated integrin signaling, is a key mechanism promoting muscle-invasion of bladder tumors." (PMID 23383328, 2013).
gastric tumors (6 papers, 2015 to 2023). "We found that MPZL3 expression is positively correlated with MET and ERBB3 expression in gastric tumors and in LUSC." (PMID 35249128, 2022). "Using mass spectrometry-based genotyping we analysed 105 hotspot, non-synonymous somatic mutations in PIK3CA and ERBB-family (EGFR, ERBB2, ERBB3 and ERBB4) genes in gastric tumour samples from 69 patients." (PMID 33933113, 2021).
nasopharyngeal carcinoma (6 papers, 2021 to 2025). A carcinoma arising from the nasopharyngeal epithelium. "In this context, silencing LACTB can inhibit the metastasis of nasopharyngeal carcinoma by inhibiting ERBB3/EGFR signal transduction and increasing the stability of histone H3." (PMID 38149985, 2023).
intestinal tumors (5 papers, 2014 to 2025). "Serum and EGF-starved HC11 cells cultured for 24 h with BKM120 revealed upregulation of Erbb3 mRNA, consistent with previous observations that PI3K inhibition causes increased Erbb3 gene expression in breast, lung, and intestinal tumor cells." (PMID 28886748, 2017). "Our study highlights the importance of regulators of intestinal tumor progression that are dependent on the ERBB3 signaling pathway." (PMID 34843459, 2021). "Therefore, the requirement for the ERBB3 signaling pathway in intestinal tumor progression could result from its unique role of linking EGFR signaling to PI3K/AKT, thus activating the PI3K pathway to promote cell proliferation." (PMID 34843459, 2021). "S. flexneri C.11 and its metabolites enhanced the binding of ERBB3 to Nrg1, activating the PI3K-AKT and mTOR pathways, which subsequently promoted the malignant transformation of normal intestinal epithelial cells and progression of intestinal tumors in mice." (PMID 40911847, 2025).
invasive ductal carcinomas (5 papers, 1998 to 2024). "It was found that the overexpression of c-erbB3 protein was observed in 67% (6/9) of comedo DCIS, 52% (44/84) of invasive ductal carcinomas, 71% (5/7) of carcinomas containing both the in situ and invasive lesions and 25% (1/4) of invasive lobular carcinomas." (PMID 9823984, 1998).
invasive lobular carcinomas (5 papers, 1998 to 2025). "Our study aims to determine ERBB2 and ERBB3 mutations frequencies in grade 3 and/or ERBB2-positive invasive lobular breast carcinomas (ILC)." (PMID 27602491, 2016).
meningioma (5 papers, 2021 to 2026). A generally slow growing tumor attached to the dura mater. "In meningiomas, aberrant activation of EphA2 and EphB1 promotes proliferation through engagement with mTOR and ERBB3 signaling pathways." (PMID 41200151, 2025). "Also, the combination more effectively blocked ligand-mediated phosphorylation of EGFR, ErbB3, and IGF-1R and elicited major changes in the expression of genes, including the upstream regulators of several signaling networks important for meningioma growth." (PMID 41417846, 2026).
neuroblastoma (5 papers, 2011 to 2024). Neuroblastoma (NB) is the most common solid, extracranial childhood tumor. "Neuroblastomas with a mesenchymal phenotype are considered high risk and more resistant to chemotherapy, making ERBB3 an interesting target in neuroblastoma research." (PMID 36181342, 2023). "We found two ERBB family members, ERBB4 and ERBB3, and P‐gp to be upregulated in resistant neuroblastoma cell lines." (PMID 36181342, 2023).
Obesity (5 papers, 2016 to 2025). Accumulation of substantial excess body fat. "In addition, the brown fat–enriched secreted factor NRG4 has been proposed as a potential target to treat obesity-associated disorders, which primarily signals through ERBB3 to regulate diverse biological processes." (PMID 34176482, 2021). "As a novel endocrine factor, circulating Nrg4 may activate the receptor kinases ErbB3 and ErbB4 and coordinate glucose and lipid homeostasis in obesity." (PMID 27772531, 2016). "Additionally, genetic studies have shown that ERBB3 is responsible for variations in the LDL-C serum concentration, and plays a role in lipid homeostasis and obesity." (PMID 34176482, 2021).
asthma (4 papers, 2020 to 2024). "Furthermore, we obtained regional association plots close to these six shared genetic loci from FUMA and confirmed that one common locus at 12q13.2 (where RAB5B and ERBB3 are located) is associated with asthma and GERD." (PMID 39223263, 2024). "Recently, ErbB3 expression has a potential association with a severe asthma phenotype." (PMID 33217964, 2020). "The MAGMA analysis identified a distinct signal at locus 12q13.2 that is associated with both asthma and GERD and also corresponds to two pleiotropic genes (i.e., RAB5B and ERBB3) identified in the gene-based MAGMA results." (PMID 39223263, 2024). "In addition, ERBB3, IL1R1, IL1RL2, IL6R, LRRC32, STAT6, and TNFRSF6B have been strongly linked to allergic diseases, such as asthma and rhinitis." (PMID 38773393, 2024). "The relevance between ErbB3 and ErbB4 and asthma pathogenesis is an emerging research field." (PMID 33217964, 2020). "ErbB3 might be a potential therapeutic target for patients with the severe asthma phenotype with IL-17 induced neutrophilic inflammation accompanied by airway hyperresponsiveness." (PMID 33217964, 2020). "After comparison, asthma and GERD were found to share six genes (ERBB3, RBM6, HLA-B, SDK1, RERG, RAB5B), one of which, ERBB3, was also significantly associated with both eczema and GERD." (PMID 39223263, 2024).
autoimmune disease (4 papers, 2015 to 2024). A disorder resulting from loss of function or tissue destruction of an organ or multiple organs, arising from humoral or cellular immune responses of the individual to their own tissue constituents. "IL1RL2, IL6R, ERBB3, ICAM1, IL1R1, and GALK1 were also enriched in categories like immune system disease, autoimmune disease, skin disease, and disease of anatomical entity." (PMID 38773393, 2024).
heart failure (4 papers, 2013 to 2024). Inability of the heart to pump blood at an adequate rate to meet tissue metabolic requirements. "Our finding that low circulating ERBB3 protein is associated with LV dysfunction and heart failure is further supported by data from patients receiving cancer therapeutics targeting ERBB2." (PMID 39180332, 2024). "Participants in the lowest quartile of circulating ERBB3 or highest quartile of circulating HSPA2 had increased incident heart failure and cardiovascular death vs. all other quartiles." (PMID 39180332, 2024). "ERBB3 mRNA expression levels on the surface of monocytes were reported to be inversely correlated with tumor necrosis factor alpha in subjects with heart failure but not in human subjects without heart failure." (PMID 34176482, 2021). "We detected methylation differences in pathways related to heart disease, but also in genes with yet unknown function in DCM or heart failure, namely Lymphocyte antigen 75 (LY75), Tyrosine kinase-type cell surface receptor HER3 (ERBB3), Homeobox B13 (HOXB13) and Adenosine receptor A2A (ADORA2A)." (PMID 23341106, 2013).
Hypertension (4 papers, 2021 to 2025). The presence of chronic increased pressure in the systemic arterial system. "The ERBB3 rs705708 A allele was associated with a lower prevalence of hypertension, indicating a potentially protective role." (PMID 41573461, 2025). "Taken together, BMI, gender, and drinking all potentially modulate the association between ERBB3 levels and hypertension in overweight individuals." (PMID 34176482, 2021). "Plasma ERBB3 levels were negatively associated with hypertension and overweight among men (OR 0.054, 95 % CI 0.007–0.412) and drinking (OR 0.002, 95 % CI 0.000–0.101)." (PMID 34176482, 2021). "The aim of this study was to assess the association between ERBB3 levels and hypertension in overweight Chinese patients." (PMID 34176482, 2021). "In addition, ERBB3 participates in neutrophil survival and ERBB3 inhibitors play positive roles in accelerating inflammation resolution, which is a known predisposing factor for the development and progression of hypertension and overweight." (PMID 34176482, 2021). "This study is the first to demonstrate the importance of ERBB3 levels in overweight patients with hypertension." (PMID 34176482, 2021). "In summary, our results provide the first demonstration that the expression of ERBB3 was significantly downregulated in overweight individuals with hypertension, and that BMI, gender, and drinking all potentially modulate the process." (PMID 34176482, 2021). "ERBB3 may contribute to the pathogenesis of hypertension in overweight patients, with BMI, gender, and drinking all potentially modulating the process." (PMID 34176482, 2021). "We observed a negative association between ERBB3 levels and hypertension with overweight among only men and drinkers." (PMID 34176482, 2021). "Further larger studies may help to elucidate the relationship and role of ERBB3 levels in the pathogenesis of hypertension in overweight individuals." (PMID 34176482, 2021). "Thus, we hypothesized that the ERBB3 may participate in the process that leads to the occurrence and development of hypertension in the and overweight context." (PMID 34176482, 2021). "Thus, it is reasonable to consider that the plasma ERBB3 levels might play an important role in the regulation of hypertension in overweight by affecting IGF-IR." (PMID 34176482, 2021). "However, the mechanisms that link ERBB3 and hypertension and overweight are currently unclear." (PMID 34176482, 2021).
liver fibrosis (4 papers, 2021 to 2025). "The overexpression of miR-148a downregulates ERBB3, which is required for the activation of hepatic stellate cells and liver fibrosis." (PMID 35328424, 2022). "Furthermore, the epidermal growth factor receptor (EGFR) and its interactive signaling partner Erb-B2 receptor tyrosine kinase 3 (ERBB3) axis in hepatocytes is essential for the recruitment of profibrotic Ly6Chi monocytes in CCl4-induced liver fibrosis." (PMID 41479922, 2025).
prostate tumor (4 papers, 2012 to 2024). "Moreover, recombinant humanized ERBB2 monoclonal antibody pertuzumab prevents dimerization of ERBB2 with EGFR and ERBB3 to prevent activation of downstream pathways, which is demonstrated to be inhibiting breast and prostate tumor growth." (PMID 38216592, 2024). "Interestingly, ERBB3 mRNA levels were significantly increased in prostate tumors compared with matched normal tissues." (PMID 31792211, 2019). "As prostate tumours develop resistance therapy through compensatory pathways regulating ErbB3 expression and localization, anti-ErbB3 therapeutic antibodies could be used for tumours displaying ErbB3185kDa overexpression and/or nuclear localization but not for tumour expressing ErbB380kDa." (PMID 27191720, 2016). "Moreover, 3 genes STAT1, ERBB3, P21 (CDKN1A) were found to be associated with ‘prostatic neoplasms regulation of progression through cell cycle’ and 1 gene STAT1 is associated with ‘prostatic neoplasms inflammatory response’." (PMID 22870216, 2012).